BRCA1 (BRCA1 DNA repair associated)
Diseases named in the same sentence as BRCA1 in open-access papers (continued):
Sharing a sentence is not in itself a finding about the gene and the disease.
cancer (continued). "BRCA1- or BRCA2-deficient cells are sensitive to siRNA-mediated knockdown or chemical inhibition of PARP, leading to the clinical testing of PARP inhibitors as potential anti-cancer drugs in BRCA1- or BRCA2-deficient cancers." (PMID 24792170, 2014). "Patients with BRCA-associated cancers usually lack wild-type BRCA1 or BRCA2 in tumor cells but normal cells retain a single wild-type copy of the gene." (PMID 25136623, 2014). "Based on the interaction of synthetic lethality that has been described between PARP1 and both BRCA1 and BRCA2, we hypothesize that this and other genes involved in the BER pathway could potentially be associated with cancer risk in BRCA1/2 mutation carriers." (PMID 24698998, 2014). "The PI3K/AKT pathway is constitutively active in BRCA1-defective human cancer cells." (PMID 25426449, 2014). "In this study, we compared BRCA1/2 mutation carriers with cancer and BRCA1/2 mutation carriers without cancer, predominantly to investigate the possibility of using TL as a method of risk stratification amongst BRCA1/2 mutation carriers." (PMID 24489760, 2014). "Panels included comprehensive analysis of 14–22 cancer susceptibility genes (BRCA1 and BRCA2 not included), depending on the panel ordered (BreastNext, OvaNext, ColoNext, or CancerNext)." (PMID 24763289, 2014). "Here we show that BRCA1 expression is also critical for vitamin D3-mediated inhibition of ER positive and ER negative breast cancer cell proliferation, as well as that of mammosphere cultures enriched with stem-like cancer cells." (PMID 25460500, 2014). "The results of this study may be used to improve the efficacy of the current therapeutic methods in cancers specifically with amplified Aur A/B and inactivated BRCA1/2." (PMID 24775809, 2014). "Estimates of cancer risk are variable across different studies; nevertheless, two large meta-analyses, resulting from a total of 31 published studies, estimated an OC risk to age 70 of 49% for BRCA1 and 18% for BRCA2 and of 39% for BRCA1 and 11% for BRCA2." (PMID 25136623, 2014). "Most of the deleterious BRCA1 and BRCA2 variants characterized thus far introduce stop codons or frame-shifts that result in premature truncation of the protein, the consequences of which manifest as cancer at relatively early ages." (PMID 25011685, 2014). "The expression of breast cancer 1, early onset (BRCA1), RAD51, bloom syndrome, RecQ helicase-like (BLM), flap-endonuclease 1 (FEN1), uracil-DNA glycosylase (UNG), damage-specific DNA binding protein 2 (DDB2) and exonuclease 1 (EXO1) were significantly suppressed after 24 h ZEA treatment." (PMID 24788721, 2014). "There have been cases in which multi-gene panels detected pathogenic mutations that would not have been identified if BRCA1/2 testing alone had been used, leading to a change in care and the early detection of cancers." (PMID 25593598, 2014). "A Phase I clinical trial of patients with solid tumors using MK-4827 was shown to have favorable pharmacokinetics, inhibited PARP activity effectively, is well tolerated and has anti-tumor activity in carriers of BRCA1 and BRCA2 mutations and patients with sporadic cancers." (PMID 24795863, 2014). "A high proportion of carriers of BRCA1 mutations do not have a strong family history of either type of cancer and it is therefore unreliable to rely on family history in order to decide upon whom to test." (PMID 24770866, 2014). "In contrast to CDKi, Bortezomib primarily affects the homologous repair system itself, resulting in synthetic lethality in CCNE1-amplified cancer cells: a genome-wide shRNA screen in 102 cancer cell lines revealed that BRCA1 was specifically required in CCNE1-amplified cell lines." (PMID 24624361, 2014). "BRCA1 and vitamin D3 are known for their anti-proliferative effects towards cancer cells." (PMID 25460500, 2014).
cancer (continued). "Others and we have reported that the mutual suppression between Aur A/B and BRCA1/2 may manipulate cancer cell growth and tumorigenesis, however, the interactive regulation and mechanism between these molecules are still elusive." (PMID 24775809, 2014). "The inability of these murine cancer cells to restore functional Brca1 expression may explain their sustained platinum sensitivity." (PMID 24624361, 2014). "Rare exonic, non-truncating variants in known cancer susceptibility genes such as BRCA1 and BRCA2 are problematic for genetic counseling and clinical management of relevant families." (PMID 24489791, 2014). "In a series comparing the methylation status of BRCA1 among tumor samples obtained from patients with benign ovarian tumors, borderline tumors as well as carcinomas, promoter methylation was detected in 31% of carcinomas but in none of the benign or borderline tumors." (PMID 24821107, 2014). "For these patients, enhancement of the BRCA1 gene function by targeted DIM impact may be particularly essential for prevention of cancer progression." (PMID 24325835, 2013). "More recently, PARP moved into the spotlight with the discovery that PARP inhibition in both cancer cell lines and human tumors lacking BRCA1 or BRCA2 is selectively cytotoxic compared to non-mutation containing tumors." (PMID 24098868, 2013). "This suggests that hypoxia may already play a role in the DCIS stage of BRCA1 and BRCA2 germline mutation related breast carcinogenesis, and may also drive cancer progression." (PMID 23409121, 2013). "The staining was more intensive in BRCA1-2 related cancers than in BRCAX and in sporadic cancers." (PMID 23326384, 2013). "Olaparib has previously been evaluated in combination with chemotherapy in patients with BRCA1/2-mutant cancer or sporadic cancer; the majority of these trials involved treatment combinations that were expected to be synergistic due to their effects on DNA repair and hence potentiate myelotoxicity." (PMID 24063698, 2013). "Our models are not intended to predict the probability of the three cancers among women known to be at much higher than average risk, e.g., women with a mutation in BRCA1 or BRCA2 or with hereditary non-polyposis colorectal cancer (HNPCC)." (PMID 23935463, 2013). "Given the availability of effective therapies that exploit defects in homologous recombination, such as PARP-1 inhibitors and cisplatin, it is increasingly important to determine whether these therapies are likely to be effective in ER+BRCA1-mutant cancers." (PMID 24137399, 2013). "The association between tumor Nmut and treatment outcome appears largely in cancers with BRCA1 mutation, but not in those cancer with BRCA1 epigenetic alteration." (PMID 24265793, 2013). "Due to KAP1’s feeble involvement in controlling cellular proliferation, BRCA1 has been speculated to be the one responsible for regulating cancer cell proliferation through its interaction with ZBRK1, a conjecture that needs to be further investigated." (PMID 23991171, 2013). "Moreover, we believe that cucurbitacin B interferes with apoptosis and cell cycle control machineries since survivin was inhibited while p21/Waf1 and p27Kip1 were upregulated in the cancer cells with defective BRCA1." (PMID 23393598, 2013). "It was presented to a French cohort of female cancer-free BRCA1/2 mutation carriers and non-carriers (N = 568)." (PMID 23680028, 2013). "Fifty percent of the unrelated patients with hormone receptor-negative tumors carried BRCA1 mutations, percentage increasing to 83% in cases with familial history of cancer." (PMID 23469205, 2013).
cancer (continued). "This suggests that hypoxia may already play a role at the DCIS stage of BRCA1 and BRCA2 germline mutation-related breast carcinogenesis, and may also drive cancer progression." (PMID 23409121, 2013). "Numerous studies have demonstrated that the cancer stem cell phenotype is heterogeneous with one study showing at least two distinct populations with cancer stem cell characteristics and Notch1 expression in cell lines derived from a Brca1 knockout mouse model." (PMID 23863842, 2013). "Patients were referred to a French family cancer clinic and had been previously tested negative for a BRCA1/2 mutation." (PMID 24139550, 2013). "VEGF expression in BRCA1-2 carriers was higher than in BRCAX cancer tissues (p = 0.0001)." (PMID 23326384, 2013). "Although there is considerable information on the molecular interactions of PARP and BRCA1- and BRCA2-deficient cancers, very little is known of the PARP inhibition effect upon cancers proficient in DNA double-strand break repair after ionizing radiation or after stalled replication forks." (PMID 23396107, 2013). "As a consequence of telomerase inhibition, over-expression of wild-type BRCA1 but not a cancer-associated mutant (Cys61Gly) caused telomere shortening in several tumor cell lines." (PMID 23802008, 2013). "However, recent evidence has shown that DBC1 has its own role in the progression of human cancers by inhibiting the tumor suppressors BRCA1 and SUV39H1 methyltransferase, and is involved in the regulation of androgen receptor and estrogen receptor α." (PMID 24019980, 2013). "BRCA1 has shown to regulate sensitivity of cancer cells to some chemotherapeutic agents." (PMID 23393598, 2013). "Nonetheless, mutations in the BRCA1 gene do not give confidence to transform normal cells into cancer cells, and other factors are essential to conduct neoplasia." (PMID 23941236, 2013). "Moreover, mutations in some of DDR genes (ATM, BRCA1, BARD1, etc.)are associated with cancer formation in animals." (PMID 24833228, 2013). "In order to fully understand the effects of altered splice isoform ratios in BRCA1-related cancer, it will be necessary to know the roles of each isoform individually and to understand the combined roles of different isoforms both in health and in tumorigenesis." (PMID 22615956, 2012). "For example, aberrant alternative splicing of certain tumor suppressors, such as breast cancer 1 and 2 (BRCA1/2), Wilms tumor 1 (WT1), and adenomatous polyposis coli (APC), results in mutations that account for inherited and sporadic susceptibility to cancer." (PMID 23236423, 2012). "We studied 39 consecutive NSCLC patients and measured the expression of six molecular markers (MDR-1, LRP, RRM-1, EGFR, ERCC-1, BRCA-1) in their primary tumors and metastatic lymph nodes and four well-known serum markers for cancer (NSE, CEA, CA-125, CYFRA 21-1)." (PMID 22890830, 2012). "Most of these genes belong to several cancer-associated genes such as MYC and BRCA1." (PMID 22615874, 2012). "When censoring patients harboring the SNP285C/309G haplotype from our analyses, we found BRCA1 related cancer cases carrying the SNP309TG and SNP309GG genotypes to be on average 3.1 year younger at time of diagnoses as compared to carriers of the SNP309TT genotype." (PMID 23039163, 2012). "BRCA1-associated cancers differ from non-hereditary cancers for a range of pathologic and molecular factors, including tumor grade and histologic appearance." (PMID 22817698, 2012). "It is due to topological analyses that we were able to extract genes which have been reported to be highly associated with cancer, such as BRCA1, ageing, immune response, etc., which would not have been present under normal conditions." (PMID 22594378, 2012). "Furthermore, we also were able to identify genes such as BRCA1, ABCA1, TNFRSF1B, MLLT11 that have been associated with various types of cancers." (PMID 22594378, 2012).
cancer (continued). "It has been suggested that BrCa1 helps to maintain fatty acid biosynthesis and lipogenesis under control in normal cells, whereas mutations in the BRCT domains of BrCa1 can abolish the regulation of ACC and lead to elevated lipogenesis, which is an important requirement for cancer cell growth." (PMID 22666314, 2012). "BRCA1 also protects cancer cells against oxidative stress by regulating antioxidant responses." (PMID 25969759, 2012). "For the three cancer datasets, three ranked lists that contain the BRCA1 hub are produced." (PMID 22253694, 2012). "The interlinked network of BRCA1/BARD1, RHAMM, Aurora A, and TPX2 is important for efficient apicobasal polarity of epithelial cells, and disruption of this through altered microtubule dynamics or altered mitotic spindle can increase the risk of cancer." (PMID 24278741, 2012). "For ethaRAPTA, the Ru-modified BRCA1 may lose its functions in cancerous cells that ultimately result in cancer cell death." (PMID 23202946, 2012). "Inactivation of BRCA1 alone is sufficient to increase U6 levels in cancer cells." (PMID 21914171, 2011). "Structural and functional changes of mutated proteins caused by different BRCA1 mutations are not identical and can lead to various phenotypes of cancers (genotype-phenotype correlations)." (PMID 22032251, 2011). "To overcome this problem we also investigated the prevalence of breast, ovarian and other cancer localizations among all the 1st and 2nd degree relatives of the carriers of both BRCA1 founder mutations irrespective of family composition." (PMID 22032251, 2011). "Even when accurately reported, well collected and verified cancer family history is often uninformative, unless extreme, as it is neither sensitive nor specific to BRCA1 mutation status." (PMID 21343941, 2011). "Genomic instability and cancer susceptibility are increased in the absence of Mdc1, Rnf8, 53bp1 or Brca1." (PMID 21552324, 2011). "We additionally analyzed telomeres in 12 pairs of affected mothers from BRCA1/2 families and their respective daughters who were mutation carriers but did not develop cancer to date." (PMID 21829373, 2011). "One may expect that the newly acquired BRCA1 proficiency will result in sensitization of the cancer cells to estrogen antagonists and taxanes." (PMID 21819606, 2011). "The expression of TFII-I would be therapeutically beneficial by affecting different TFII-I-mediated regulatory pathways together with BRCA1 and the failure of binding between BRCA1 and TFII-I may be a key event in cancer predisposition." (PMID 21407215, 2011). "Hence, there has been great interest in elucidating the molecular mechanisms in BRCA1 cancers to identify potential biomarkers and drug targets." (PMID 22032724, 2011). "The five most significant BioCarta pathways were first multivalent nuclear factor, FAS signaling pathway (CD95), p38 MAPK signaling pathway, control of skeletal myogenesis by HDAC and calcium/calmodulin-dependent kinase (CaMK), role of BRCA1, BRCA2, and ATR in cancer susceptibility." (PMID 21836821, 2011). "The one ER+ cancer demonstrating BRCA1 methylation in our series was not typical of the ER+ cancers with loss of wt BRCA1, being a low grade (tubular) carcinoma with a low mitotic rate." (PMID 21080930, 2010). "Furthermore, the networks related to cell cycle, cancer and nervous system development and function showed that several genes such as Nfkb2, NFκBia, BRCA1, Vegf, Jag2, Notch1, EGR1, FoxS1 and collagen type I were regulated by TNF." (PMID 20967264, 2010). "In particular, grade 3 ER+ BRCA1 cancers less often had a high mitotic rate (P < 0.001), geographic necrosis/fibrotic focus (P = 0.002), or pushing/unknown margins (P < 0.001)." (PMID 20149218, 2010). "However, the frequency of this phenomenon, particularly for ER+ BRCA1 cancers, remains to be more clearly defined." (PMID 20149218, 2010).
cancer (continued). "Further, Antoniou and colleagues have shown that modifying loci associated with BRCA2 cancers, but not with BRCA1 carriers, parallel those associated with ER-positive disease in the general population." (PMID 20482762, 2010). "Therefore, it has been suggested that ER negativity is intrinsic to BRCA1 cancers and reflects the cell of origin of these tumors." (PMID 21080930, 2010). "The overall annual incidence rates irrespective of age in those who had no prior or prevalent cancer, were 2.7% for BRCA1 founder mutations, 3.6% for less frequent BRCA1 mutations, and 2.5% for BRCA2 mutations." (PMID 20180971, 2010). "Yet, miR-451 may have roles in breast- and other cancers, and maps to an amplicon that includes HER2 and BRCA1, which are commonly amplified in breast- and other cancers." (PMID 20976003, 2010). "Immunostains were less helpful in distinguishing ER+ cancers with and without loss of the wt BRCA1 allele." (PMID 21080930, 2010). "In ER- cancers, the mean age at diagnosis of first invasive cancers with or without loss of wt BRCA1 was 42 years and 33.5 years, respectively." (PMID 21080930, 2010). "BRCA1 gene methylation was determined on all cancers in which sufficient DNA was available." (PMID 21080930, 2010). "Of the 12 cancers without loss of wt BRCA1, 10 (4 ER-, 6 ER+) had protein truncating lesions and 2 (both ER+) had a splice site mutation resulting in an in-frame deletion." (PMID 21080930, 2010). "One of nine cancers tested that retained wt BRCA1 demonstrated BRCA1 gene methylation." (PMID 21080930, 2010). "None of the BRCA1 mutation carriers was identified by group 1 clinical diagnostic criteria and 8 of them reported only isolated cases of index cancer among blood relatives." (PMID 21034437, 2010). "If, in fact, ER negativity is intrinsic to BRCA1 cancers, this would raise the possibility that at least some BRCA1 ER+ cancers may be 'incidental', and not caused by a complete loss of BRCA1 function in the cancer cells." (PMID 20149218, 2010). "Adding EGFR staining increased the sensitivity of identifying ER- cancers with loss of wt BRCA1 (28/28; 100%), however it lowered the specificity as three of four of the ER- cancers without loss of wt BRCA1 (75%) stained for EGFR." (PMID 21080930, 2010). "Thus, a logical therapeutic option is to restore the tumor suppressor function of BRCA1 in cancer cells in order to suppress cell proliferation." (PMID 20182637, 2010). "Of these cancers 34/42 (81.0%) ER+ and 31/35 (88.6%) ER- had LOH with loss of the wt BRCA1 allele; the difference in frequency of loss of wt BRCA1 between ER+ and ER- cancers was not significant (P = 0.53)." (PMID 21080930, 2010). "Larger studies are necessary to explore the possibility that basal epithelial markers may mark ER+ cancers that have lost wt BRCA1." (PMID 21080930, 2010). "Cells that lack a functional BRCA1 or BRCA2 have a deficiency in the repair of DNA double-strand breaks, which is probably one of the mechanisms behind their association with increased cancer predisposition." (PMID 20979652, 2010). "In multinomial logistic regression, ER+ BRCA1-associated cancers retaining wt BRCA1 were significantly more likely than cancers without wt BRCA1 to have a low mitotic rate (OR, 5.16; 95% CI, 1.91 to ∞)." (PMID 21080930, 2010). "The Cancer Pathway Finder Array analysis identified numerous cancer-associated genes exhibiting substantial over expression in trisomic BG01V APCs relative to diploid H9 APCs, including CDC25A, IGF1, MMP9, FGFR2, BRCA1, CASP8 and TERT1." (PMID 20423517, 2010). "This implies that the risk of cancer is most likely higher than those with a ‘true negative’ (i.e., those with a negative genetic test result in a family with a known BRCA1 or BRCA2 mutation) genetic test result." (PMID 19088722, 2009). "On the other hand, BRCA2, but not the BRCA1 gene, was significantly linked to the development of cancer outside the breast–ovarian axis." (PMID 19329713, 2009).